FLT3 (fms related receptor tyrosine kinase 3)
Diseases named in the same sentence as FLT3 in open-access papers (continued):
Sharing a sentence is not in itself a finding about the gene and the disease.
tumor (continued). "Further studies in in vivo tumor xenograft studies are required to evaluate the effects of specific FLT3 inhibitors such as tandutinib on the resistance of cancer cells to antineoplastic drugs." (PMID 23525656, 2013). "Herein, this untraditional approach was further evaluated by performing PRL-3 mAb therapy in mice carrying tumours formed by TF1-ITD cells expressed both FLT3-ITD and PRL-3 proteins." (PMID 23929599, 2013). "Quizartinib was demonstrated to have high efficacy and tolerability in tumor xenograft models that express a FLT3 ITD mutant kinase." (PMID 23497317, 2013). "Sunitinib, a multikinase inhibitor that targets VEGFR-2, PDGFR, KIT, and FLT3, inhibited VEGFR-2 phosphorylation and VEGF-induced vascular permeability and caused tumor regression, growth arrest, or growth inhibition in tumor xenografts." (PMID 23057939, 2012). "This suggested that miR-16 is acting like a tumour suppressor gene in FLT3/ITD-mediated leukemic transformation." (PMID 22970245, 2012). "The data suggests that miR-16 is acting as a tumour suppressor gene in FLT3/ITD-mediated leukemic transformation." (PMID 22970245, 2012). "BPR1J-097 also showed favourable pharmacokinetic property and pronounced dose-dependent tumour growth inhibition and regression in FLT3-driven AML murine xenograft models." (PMID 22187040, 2012). "Moreover, Compound 14 demonstrated an impressive pharmacokinetic profile and exerted significant antitumor efficacy in the FLT3-ITD-positive AML xenograft mouse model (approximately 80% decrease in tumor mass)." (PMID 42262889, 2026). "This limitation may result from tumor cell resistance to FLT3 inhibitors and the limited ability of BCL-2 inhibitors to induce apoptosis in tumor cells, which relies on alternative antiapoptotic pathways." (PMID 40016600, 2025). "Furthermore, gilteritinib combined with chemotherapy has been shown to reduce tumor volume more effectively than either agent alone in FLT3-ITD + AML cell lines and xenograft mouse models." (PMID 41199910, 2025). "It targets several receptors implicated in tumor growth and angiogenesis, including KIT, VEGFR2 (KDR), VEGFR3 (FLT4), and FLT3, making it a candidate for treating GISTs, particularly in patients who have developed resistance to standard therapies like imatinib." (PMID 40733131, 2025). "In addition, there are strong selective genes such as TDGF1, EGFR, and FLT3, whose downregulation can also inhibit tumor growth." (PMID 40046734, 2025). "Notably, IHCH9033 maintained its potency in both FLT3i-resistant AML cell lines and primary-resistant patient samples, and exerted strong synergy with the FLT3i quizartinib, leading to tumor regression in FLT3-ITD/TKD AML xenografts." (PMID 39955584, 2025). "In addition, IGV visualization confirmed significant enrichment of eccDNA at genomic loci of tumor-related genes such as FLT3, RUNX1, CD33, and HMGB1." (PMID 41278279, 2025). "Furthermore, another novel oral PROTAC (A20) targeting FLT3-ITD demonstrated complete tumor regression and improved survival in AML xenograft models." (PMID 41226551, 2025). "These implied that FLT3 might serve as a tumor suppressor gene and could be upregulated in feedback with the increase of tumor malignancy; however, the specific function and molecular mechanism need to be further studied." (PMID 39311766, 2024). "Discussion: FLT3 inhibitors monotherapy has shown significant anti-tumor effect in clinic, and the effectiveness may be further improved through combination medication." (PMID 38828446, 2024). "The ADMIRAL trial demonstrated that patients treated with 80 mg/d of gilteritinib have a tumor objective response rate (ORR) of 40% of all AML patients, regardless of whether they displayed the mutation—an ORR of 52% in those with the FLT3 mutation." (PMID 39273395, 2024).
tumor (continued). "Moreover, FLT3, encoding a class III receptor tyrosine kinase, exhibited reduced expression in a significant proportion of HCC patients, which was consistent with our findings that FLT3 was decreased in HCC tumor tissues." (PMID 38468074, 2024). "In vitro studies showed that FLT3 inhibitor had a synergistic anti-tumor effect with venetoclax." (PMID 37120593, 2023). "Moreover, the dual inhibition of BCR::ABL1 and FLT3 via combined treatment of imatinib with quizartinib further impaired tumor growth." (PMID 37932786, 2023). "For the patients with FLT3mut, the high CRc might be attributed to the synergistic anti-tumor effect of VAH combined with FLT3 inhibitors." (PMID 37120593, 2023). "In contrast, the protective factors SOSC2 and FLT3 expression had a negative association with tumor stage." (PMID 37346073, 2023). "Demonstrated safety, tolerability, and preliminary efficacy data generated on the current trial support formulation of FN-1501 that enables convenient delivery in order to further test the therapeutic value of a TKI with significant impact on FLT3 and in biologically appropriate tumor genotype(s)." (PMID 37174019, 2023). "The immunity to FLT3 elicited by VRP-FLT3 might serve as a trigger and raise a subsequent immune response against additional antigens on the tumor cells." (PMID 35686131, 2022). "The simultaneous inhibiting of both FLT3-ITD and mTOR could be effective in tumor suppression in upregulated acute leukemic cells resistant to single-agent FLT3 inhibitors." (PMID 36293564, 2022). "In terms of safety, on-target, off-tumor reactivity is a concern also for anti-FLT3 CAR T-cells." (PMID 36289703, 2022). "Given the FLT3-ITD mutation, the patient began treatment with oral gilteritinib, with rapid regression of the tumor, complete disappearance of the iris component, and a significant reduction in the size of the ciliochoroidal tumor accompanied by an improvement in visual acuity." (PMID 35565314, 2022). "He relapsed again on the 21 month and was refractory to treatment with venetoclax—DEC and Gilteritinib monotherapy while the bulk tumor sequencing no longer detect any FLT3-ITD or IDH2 mutation." (PMID 35563039, 2022). "Furthermore, ferroptosis-related genes with prognostic value contribute to FLT3-ITD AML progression by regulating the tumor microenvironment." (PMID 36612069, 2022). "In addition, the prevalence of IgG2b and IgG2c subclasses among FLT3-specific IgG hinted at a potential tumor-killing effect of the VRP-FLT3 vaccine through ADCC." (PMID 35686131, 2022). "The mice were tumor free after 35 days after a single dose of anti-FLT3 CAR T-cells." (PMID 36289703, 2022). "The inhibitory effect of FM on FLT3 mutant tumor cell lines was also obvious with an IC50 < 0.1 μM." (PMID 35256594, 2022). "Together, EGFL7 stimulates Flt3/Flt3 ligand signaling in ETPs that resulted in the accumulation of immature ETPs and a paucity of circulating T cells and contributes to impaired antigen-directed cytotoxicity against tumor cells." (PMID 33804387, 2021). "The activity of multiple kinases, including FLT3, is also affected, and this multikinase inhibition might contribute to the anti-tumor effects of vandetanib, cabozantinib, and sorafenib." (PMID 33419162, 2021). "Antitumour activity of foretinib in SNU‐1 xenografts can be explained by its inhibitory effect on other oncogenic pathways including VEGFR2, PDGFR‐β, Axl, c‐Kit, Flt‐3 and Tie2 in tumour epithelial cells or a possible c‐Met activity in non‐epithelial tumour stromal cells." (PMID 33939252, 2021). "With respect to the AML-categories, a more substantial blast drop under lenalidomide was noticed in AML with defining mutations, despite the fact that the presence of driver mutations such as FLT3 and NPM1 has been linked to low cytolytic activity of the tumor microenvironment." (PMID 33704530, 2021).
tumor (continued). "Nine out of 11 patients without spliceosome/FLT3 mutations achieved tumor reduction when CA-4948 was added to venetoclax or azacitidine." (PMID 34829820, 2021). "Indeed, sorafenib inhibits the phosphorylation of various targets present in the signaling pathways of both tumor cells (i.e., CRAF, BRAF, V600E BRAF, c-KIT, and FLT-3) and in the tumor-endothelial cells (i.e., CRAF, VEGFR-2, VEGFR-3, and PDGFR-β)." (PMID 34681219, 2021). "FLT3‐targeted therapy has also been shown to improve long‐term outcome when administered as maintenance therapy of FLT3 mutated AML after allogeneic stem cell transplantation, a disease state characterised by low tumour burden and anti‐leukemic immunological mechanisms." (PMID 33817952, 2021). "Proven effects on tumor cell cycling by FLT3 inhibitors have led to many clinical trials either as a monotherapy, or as combinatorial therapy with conventional chemotherapy, with early meta-analysis suggesting a statistically significant 17% improvement in survival." (PMID 34835225, 2021). "Experiments for the molecular pathway of the FLT3 and tumor progress should be set off." (PMID 33102231, 2020). "In addition, sorafenib indirectly suppresses tumor cell proliferation through targeting c-Kit, FLT-3, VEGFR-2/3, PDGFR-β, and other tyrosine kinases, which are involved in tumor angiogenesis." (PMID 32970612, 2020). "The following tumor mutations were reported in patients with clinical benefit: cKIT (n = 1), CSF-1R (n = 1), PDGFRα (n = 2), PDGFRβ (n = 1), VEGFR1 (n = 1), VEGFR2 (n = 2), FLT3 (n = 1), FGFR2 (n = 2), RET (n = 1), and TrkA (n = 1)." (PMID 32292573, 2020). "FLT3-ITD AML has an adverse prognosis, and mutations are related to an increased tumor burden." (PMID 32284743, 2020). "The upregulated expression of the FLT3, MEF2C, NFKBIZ, and MDM2 genes in sarcoid AMs suggests the potential side effect of DEX and it may lead to increased risk of tumor cell proliferation." (PMID 32477331, 2020). "Additionally, miR-16 was found to be down-regulated in FLT3-ITD positive murine myeloid FDC-P1 cells and FLT3 inhibition tends to correct this down-regulation, therefore suggesting a tumor suppressor activity in FLT3/ITD-mediated leukemic transformation." (PMID 33519805, 2020). "Sorafenib, a multikinase inhibitor, has activities against Raf kinase and several receptor tyrosine kinases, such as vascular endothelial growth factor receptor 2, platelet-derived growth factor receptor, FLT3, Ret, and c-Kit, and inhibits tumor angiogenesis in HCC." (PMID 32548687, 2020). "A pan-PIM/FLT3 inhibitor SEL24, a type II FLT3 inhibitor MZH29, a MERTK/FLT3 inhibitor MRX-2843, a BCR-ABL inhibitor ponatinib, and a multiple tyrosine kinase inhibitor cabozantinib have exhibited anti-tumor activity in cases with FLT3-TKD, including those with the F691 pointmutation." (PMID 32722298, 2020). "Transplantation of adult BM-derived HSPC retrovirally expressing the NUP98–NSD1 fusion was reported to induce an AML phenotype in mice after a long latency with tumor cells expressing myeloid but also early stem cell-related (FLT3, CD34, and KIT) surface markers." (PMID 31681706, 2019). "Furthermore, sorafenib indirectly inhibits tumor cell proliferation by suppressing tumor angiogenesis via targeting c-Kit, FLT-3, VEGFR-2/3, PDGFR-β, and other tyrosine kinases, which are activated in tumor angiogenesis." (PMID 31750247, 2019). "Primary AML tumor samples were selected based on having known HLA haplotypes for HLA-A, B, C and HLA-DR, and at least one or more common recurrent mutations in either NPM1, FLT3, DNMT3A, IDH1, IDH2, KIT, or RAS from previous clinical evaluation." (PMID 31291378, 2019). "Next we analyzed whether 4G8-SDIE induced an immune response specifically against FLT3+ tumor cells." (PMID 31817795, 2019). "Finally, it induces tumor regression because it is also active against FMS-like tyrosine kinase 3 (FLT-3), mast/stem cell growth factor (cKIT), TIE-2, and tropomyosin-related kinase B (TRKB)." (PMID 31151284, 2019).
tumor (continued). "Here, we investigated whether the inhibitory effects of gilteritinib on tumor growth and FLT3 signal transduction are affected by FL in the human AML cell line MOLM-13, which harbors both FLT3wt and FLT3-ITD." (PMID 31692922, 2019). "More than half of the tumor samples had normal karyotypes; nearly half (6 of 13) bore NPM1 mutation A and most (9 of 13) had FLT3-ITD mutations, likely reflecting the increased frequency of banked tumor specimens from patients with high white blood cell counts." (PMID 31291378, 2019). "Another more likely hypothesis is that this long-lasting effect, may be due to prolonged inhibition of FLT3 phosphorylation, as was shown in the case of in vivo administration of the small-molecule FLT3 inhibitor sunitinib in a tumor xenograft model." (PMID 29531216, 2018). "In a recent report, PI3K-delta inhibitor had synergistic anti-tumor activity with FLT3 inhibitors." (PMID 30514344, 2018). "We also evaluated the effects of palbociclib in an FLT3–D835Y+ subcutaneous tumor xenograft model." (PMID 30544932, 2018). "Herein, we show that SEL24-B489 specifically inhibits PIM- and FLT3-ITD- related pathways and exhibits significantly broader anti-tumor activity in AML models than selective FLT3-ITD or PIM inhibitors, underscoring its therapeutic potential for the treatment of AML." (PMID 29682194, 2018). "Additionally, mice injected with cells expressing FLT3-ITD/Y842F displayed a significant delay in tumor formation, compared to FLT3-ITD expressing cells." (PMID 28271164, 2017). "The FLT3-ITD/Y842F mutant displayed significantly delayed tumor formation in xenotransplanted mice." (PMID 28271164, 2017). "As we observed that the Y842F mutation diminishes FLT3-ITD-mediated cell viability, colony formation and tumor formation, we hypothesized that this mutation might influence FLT3-ITD-induced gene expression." (PMID 28271164, 2017). "Our study was performed to evaluate the anti-tumor activity of crotonoside and found that crotonoside could inhibit all of FLT3 and HDAC3/6, and exhibited selective inhibition pattern toward AML cells." (PMID 29262547, 2017). "Because only HSCs are capable of long-term propagation of the Flt3-ITD clone, this is to our knowledge the first demonstration of a tumor model that is dependent on propagation by a stem cell compartment which carries the relevant DNA mutation but nevertheless does not express the mutant protein." (PMID 28637883, 2017). "In a mouse xenograft model, GADS accelerated FLT3-ITD-dependent tumor formation." (PMID 26895103, 2016). "Because GADS expression potentiated cell proliferation and colony formation, we aimed to check whether GADS expression enhances FLT3-ITD-induced tumor formation in mice." (PMID 26895103, 2016). "Moreover, SLAP2 expression in lymphoid and myeloid cells inhibits FLT3-induced proliferation, colony formation, and tumor formation." (PMID 27458164, 2016). "Furthermore we have shown that treatment of FLT3-ITD AML with ibrutinib or BTK knockdown in combination with daunorubicin increases tumour apoptosis over daunorubicin alone." (PMID 26292723, 2015). "Because BEX1 expression reduced cell proliferation, inhibited colony formation and induced apoptosis, we aimed to check whether BEX1 expression delays FLT3-ITD-induced tumor formation in mice." (PMID 26046670, 2015). "In addition, BPR1J-340 exhibits favorable pharmacokinetic properties and significant anti-tumor activity in FLT3-ITD murine xenograft models." (PMID 24416160, 2014). "This inhibition profile may allow BPRJ-340 to inhibit tumor growth directly by blocking the aberrant FLT3 signaling pathway and indirectly by targeting tumor angiogenesis." (PMID 24416160, 2014). "Sorafenib is an oral multikinase inhibitor that inhibits the Ras/Raf/MAPK signaling pathway, as well as platelet-derived growth factor receptors-α and β, VEGFRs-1, 2 and 3 and c-KIT and FLT3 kinases, to prevent tumor growth by antiangiogenic, antiproliferative and/or proapoptotic effects." (PMID 24940450, 2014).
tumor (continued). "For example, sunitinib inhibits a number of growth factor receptors regulating both tumor cell proliferation/survival and tumor angiogenesis including vascular endothelial growth factor receptors, platelet-derived growth factor receptors α and β, c-Kit, FLT3, CSF1R, and RET." (PMID 24701565, 2014). "It would seem to be tumor-type specific i.e. (growth of a second graft of a different cell line is not affected by irradiation of the first graft) and is synergistic with administration of the Flt-3 (FMS-like tyrosine kinase 3) ligand." (PMID 25053129, 2014). "However, approval of these agents for FLT3-associated diseases is still challenging, which was suspected to be due to the failure to fully inhibit FLT3 in tumours and undesirable drug properties." (PMID 22187040, 2012). "In addition, BPR1J-097 showed favourable pharmacokinetic properties and significant dose-dependent tumour reduction in FLT3-ITD murine xenograft models." (PMID 22187040, 2012). "Studies have shown that G6PD mutations in patients with AML may lead to redox imbalance, which, in turn, affects tumor cell growth and drug resistance, especially in FLT3 inhibitor therapy, where G6PD-driven redox metabolism promotes the development of drug resistance." (PMID 40299448, 2025). "Thus, targeting of upstream pathways (e.g., inhibiting FLT3 via gilteritinib) in addition to treatment with rapamycin may show less resistance, better anti-tumor effects, and better mobilization of NK cells." (PMID 39273395, 2024). "The other four genes not previously discovered to be correlated with the outcome of CM may likewise be crucial for the development of tumor, which include the interleukin receptor encoding gene IL7R, cytokine receptor FLT3, complement component C1QC, histocompatibility complex HLA-DRB5." (PMID 35300397, 2022). "In addition to the good correlation between the VAF on bulk tumor sequencing and the VAF of the sub-clones harboring FLT3-ITD and IDH2 mutations, rare mutations that were below the detection limit of bulk tumor sequencing were detectable with sc-DNA sequencing." (PMID 35563039, 2022). "Sorafenib is a multi-target kinase inhibitor that blocks cell proliferation by inhibiting the MAPK pathway, and prevents tumor-associated angiogenesis by inhibiting vascular endothelial growth factor receptors (VEGFR) as well as platelet-derived growth factor receptor (PDGFR) and FLT3." (PMID 34781982, 2021). "Thus, RTK mutations, including KIT and FLT3-ITD, could activate autophagy to maintain a sufficient pool of energy substrates to sustain tumor growth and chemoresistance." (PMID 31311917, 2019). "It is a multi-kinase inhibitor of tumor growth and angiogenesis, which can significantly inhibit C and B-Raf serine/ threonine kinases, vascular endothelial growth factor receptor, platelet-derived growth factor receptor, tyrosine kinases and FLT-3 (fms related tyrosine kinase 3)." (PMID 28460436, 2017). "Importantly, potency of crenolanib to inhibit cellular proliferation as well as to induce apoptosis of the engineered Ba/F3 cell strains (harboring KIT D816V, KIT D816Y or FLT3 ITD) revealed strong correlation with the corresponding tumor cell lines (HMC1.2, p815 or MOLM14, respectively)." (PMID 29137311, 2017). "Fucoxanthin has demonstrated broad anti-tumor activity by targeting the PI3K/AKT pathway, which is a key vulnerability in FLT3-ITD-driven AML." (PMID 40735485, 2025). "When comparing the tumor tissues and the normal tissues, the expression of BRD4, EMC2, FLT3, and SIAH2 was upregulated in the tumor tissues." (PMID 40696656, 2025).